TMEM8B (transmembrane protein 8B)
Description:
May function as a regulator of the EGFR pathway. Probable tumor suppressor which may function in cell growth, proliferation and adhesion.
Synonyms: C9orf127; NGX6; NAG-5; NGX6a; FP588; LINC00950; NAG5
Tractability: Antibody: UniProt places it where antibodies can reach, with high confidence; its Gene Ontology location is reachable by antibodies, with high confidence; UniProt predicts a signal peptide or a membrane-spanning region. PROTAC: its protein half-life has been measured.
Gene: Protein-coding gene on chromosome 9 (35,814,451 to 35,865,518, forward strand). Ensembl gene ENSG00000137103.
Subcellular location: Cell membrane (Isoform 2); Cytoplasm; Nucleus; Mitochondrion; Endoplasmic reticulum
Subcellular location (Human Protein Atlas): Vesicles
Gene Ontology:
Molecular function: protein binding
Biological process: cell-matrix adhesion; regulation of mitotic cell cycle
Cellular component: cell surface; cytoplasm; endoplasmic reticulum; mitochondrion; nucleus; plasma membrane; membrane
Genetic constraint (gnomAD): Loss-of-function variants: 29 observed, 47.36 expected, observed/expected ratio (o/e) 0.61, 90% interval 0.46 to 0.83. The upper end of that interval is the gene's LOEUF score, 0.83, which puts it in group 3 of 6, group 1 being the genes least tolerant of losing a copy. Missense variants: 575 observed, 667.6 expected, observed/expected ratio (o/e) 0.86, 90% interval 0.8 to 0.92. Synonymous variants: 264 observed, 273.26 expected, observed/expected ratio (o/e) 0.97, 90% interval 0.87 to 1.07.
Homologues: Orthologues: macaque TMEM8B (99% identical), pig TMEM8B (93% identical), dog TMEM8B (93% identical), rabbit TMEM8B (93% identical), mouse Tmem8b (92% identical), rat Tmem8b (92% identical), guinea pig TMEM8B (86% identical), tropical clawed frog tmem8b (58% identical), zebrafish TMEM8B (55% identical), chimpanzee TMEM8B (51% identical), zebrafish si:dkey-84j12.1 (24% identical). Paralogues in human: PGAP6 (34% identical), MYMK (7% identical).
Diseases named in the same sentence as TMEM8B in open-access papers:
TMEM8B is named in the same sentence as 8 diseases in open-access papers, as found by Europe PMC text mining. Sharing a sentence is not in itself a finding about the gene and the disease. The quoted sentences say what the papers report.
colon carcinoma (5 papers, 2010 to 2020). "TMEM8B is a tumor metastasis inhibitor formerly known as nasopharyngeal carcinoma associated 6 (NGX6) and was originally isolated from nasopharyngeal carcinoma and colon cancer." (PMID 33333720, 2020). "The TMEM8B gene acts to inhibit metastasis and restrains proliferation by arresting cell cycle progression at the G0/G1 phase of colon cancer cells in vitro." (PMID 33333720, 2020).
glioma (1 paper, 2024). A benign or malignant brain and spinal cord tumor that arises from glial cells (astrocytes, oligodendrocytes, ependymal cells). "Correlation analysis revealed that TSPAN4 was positively correlated with ITGB1, GDF15, ITGA3 and ITGA6, and negatively correlated with CHD7, ASPDH, TMEM8B and GHITM in glioma." (PMID 39723210, 2024).
tumor (11 papers, 2009 to 2026). "In humans, TMEM8B/NGX6 has been identified as a tumor suppressor and its downregulation is associated with several cancers." (PMID 41282327, 2025). "Recently, several studies have indicated that human TMEM8b (also named NGX6 for nasopharyngeal carcinoma associated gene 6) was down-regulated in several cancer cell lines and may be a tumor suppressor." (PMID 21733186, 2011).
TMEM8B also shares sentences with these, for which no sentence is quoted: cancer (6 papers); colorectal cancer (2); nasopharyngeal carcinoma (2); colorectal tumor (1); gastric cancer (1).